BDNF (brain derived neurotrophic factor)
Diseases named in the same sentence as BDNF in open-access papers (continued):
Sharing a sentence is not in itself a finding about the gene and the disease.
depression (continued). "Both BDNF and IL-10 levels exhibited strong inverse correlations with Hamilton Depression Rating Scale (HAM-D) scores (BDNF: ρ = −0.61, p < 0.001; IL-10: ρ = −0.52), reinforcing their protective roles in mitigating depressive symptoms." (PMID 40823578, 2025). "Research shows that synaptic plasticity theory is a widely accepted mechanism significant to the pathophysiology of depression, with BDNF signaling being one of these." (PMID 40066336, 2025). "Our study is the first to demonstrate the critical role of SPP1 signaling in post‐ICH depression through modulation of the Nrf2/BDNF pathway, providing novel therapeutic targets for clinical management of this debilitating neuropsychiatric sequela." (PMID 41345421, 2025). "NLRP3 inflammasome, microglia, TNF-α, and brain-derived neurotrophic factor (BDNF) were the basis of neuroinflammation in depression." (PMID 40520890, 2025). "Rb1 downregulates miR-134 expression, thereby relieves miR-134-mediated suppression of BDNF, activates BDNF-TrkB signaling pathway, enhances synaptic plasticity, and ultimately ameliorates depression-like behaviors." (PMID 40949123, 2025). "Clinical studies in SUD and depression report increased serum BDNF levels following repeated DLPFC tDCS." (PMID 40725591, 2025). "Research in this area is still in its early stages, and definitive conclusions about BDNF’s role in depression and anxiety are yet to be established." (PMID 40491453, 2025). "Brain-derived neurotrophic factor (BDNF) plays a central role in the pathophysiology of depression and in antidepressant responses." (PMID 41340853, 2025). "Dysregulation of BDNF has been reported in both epilepsy and depression, and restoring its levels is considered a therapeutic target." (PMID 40941042, 2025). "Using a rat model of depression caused by chronic unpredictable mild stress, the antidepressant action of NMC-4 significantly normalized the reduced BDNF/PI3K/Akt pathways in the cerebral cortex of depressed rats." (PMID 40005159, 2025). "Studies highlight the role of the Sigma-1 Receptor (Sig-1R), where fecal microbiota from Sig-1R knockout mice induced depressive behaviors in healthy mice, demonstrating the gut microbiome’s influence on depression via the cAMP/CREB/BDNF signaling pathway." (PMID 40283148, 2025). "A. muciniphila and its outer membrane protein Amuc_1100 can alleviate antibiotic-induced anxiety and depression by modulating the BDNF/TrkB signaling pathway or increasing serum and hippocampal 5-HT levels." (PMID 41017972, 2025). "The results of our study reveal a significant increase in serum levels of both 5-HT and BDNF in adolescents with depression after aerobic exercise and rTMS interventions." (PMID 41477617, 2025). "NYT administration improved hippocampal BDNF levels, which ameliorated depression-like behavior and anxiety in aged mice with chronic obstructive pulmonary disease-induced anxiety and depression." (PMID 40361157, 2025). "In conclusion, our data showed that the administration of NCUR would inhibit UCMS‐induced depression, which would result in an increase in BDNF and serotonin levels." (PMID 39972664, 2025). "GAL and its receptors can also interact with noradrenaline, neuropeptide Y, brain-derived neurotrophic factor, and dopamine to regulate depression." (PMID 40048451, 2025). "Recent studies even reported > 90% specificity for their improved diagnostic accuracy of multiplex biomarker panels using BDNF with inflammatory markers, e.g., IL-6, TNF-α, to also differentiate treatment-resistant depression from other depressive subtypes." (PMID 40362507, 2025). "The TrkB-BDNF pathway is recognized as a key mechanism in TLE and depression, where decreased levels of BDNF disrupt brain plasticity in both conditions." (PMID 40941042, 2025). "Ruminococcus (decreased in depression): as a key butyrate-producing bacterium, Ruminococcus supports hippocampal BDNF expression via butyrate." (PMID 41170359, 2025).
depression (continued). "In regards to synaptic plasticity, specific neurobiological mechanistic targets for anxiety and depression include transforming growth factor β, BDNF, glycogen synthase kinase-3β, synaptophysin, and lipid peroxidation." (PMID 39851502, 2025). "Studies in depression show decreased H2K9ac at BDNF, in schizophrenia where H3K27me3 is modified at GAD1, in PTSD with repressive marks on FKBP5, and in addiction where changes in H3 acetylation impact reward circuits." (PMID 41234420, 2025). "Low BDNF expressions and levels are observed in major depressive disorders, anxiety disorders, and neurodegenerative diseases, such as AD, PD, etc.." (PMID 40076857, 2025). "Decreased BNDF level in the hippocampus results in decreased proliferation of hippocampal neurons and decreased BDNF levels play a role in the pathogenesis of depression." (PMID 39962033, 2025). "A lower function of the descending pain modulatory systems, along with a higher level of brain-derived neurotrophic factor was shown to differentiate from depression." (PMID 40172661, 2025). "In this research, the concentration of 5-HT was chosen to reflect the endocrine mechanism of depression, while the concentration of BDNF was selected to represent the neurotrophic factor mechanism." (PMID 41477617, 2025). "Studies using peripheral BDNF as a marker have found that it is reduced in depression, anxiety, and several other psychiatric disorders, as well as after stroke and in neurodegenerative disorders." (PMID 39613915, 2025). "RT also stimulates neuroplasticity (e.g., via increased brain-derived neurotrophic factor, BDNF) and reduces systemic inflammation and cortisol levels, thereby mitigating some of the neuroendocrine stress responses linked to depression." (PMID 41473524, 2025). "Fifthly, muscles not only produce creatinine but also brain-derived neurotrophic factor (BDNF), which is significantly associated with depression." (PMID 40071279, 2025). "Consistent with this, exposure to a chronic mild stress paradigm that induces depression altered the trafficking of BDNF mRNA in rodents." (PMID 41254423, 2025). "Exercise can upregulate brain-derived neurotrophic factor (BDNF), which assists brain repair while counteracting anxiety and depression." (PMID 40559330, 2025). "Studies have shown that regular physical activity can promote the synthesis of mood-regulating neurotransmitters such as 5-HT and BDNF, while lowering levels of stress hormones such as cortisol, thereby helping to alleviate symptoms of depression and anxiety." (PMID 40680227, 2025). "For example, increased methylation of the BDNF promoter has been observed in individuals with depression and correlates with reduced BDNF expression in post-mortem brain tissue." (PMID 41303496, 2025). "Downregulation of brain-derived neurotrophic factor (BDNF) in the hippocampus and prefrontal cortex is strongly associated with cognitive impairments in depression." (PMID 41356690, 2025). "The interplay between tPA and BDNF represents a significant area of investigation in depression research." (PMID 40725146, 2025). "Depression is frequently accompanied by decreased BDNF levels and compromised TrkB signaling, which lead to neuronal atrophy, synaptic dysfunction, and decreased neuroplasticity." (PMID 40149774, 2025). "DHM improves both neuralgia and depression-like behaviors in diabetic rats by modulating the BDNF/TrkB signaling pathway." (PMID 40740995, 2025). "After eight weeks, participants showed not only improved depression scores (via the Beck Depression Inventory), but also increased serum levels of brain-derived neurotrophic factor (BDNF), a key molecule involved in neuroplasticity and mood regulation." (PMID 41471921, 2025). "Iron overload–induced neuroinflammation and ferroptosis play a central role in the pathogenesis of depression by disrupting antioxidant defenses, impairing BDNF signaling, and triggering neuronal degeneration." (PMID 40951640, 2025).
depression (continued). "The review indicates some potential benefits, such as confirming that BDNF incretion attenuates depression-like behavior and reverses anhedonia or indicating a dose-dependent role of hippocampal neurotrophins in vitamin D-linked mood regulation." (PMID 40871684, 2025). "For example, (R)-ketamine induced a beneficial effect on BDNF/TrkB signaling in the SDS model of depression, which correlated with an antidepressant-like effect and was more potent than (S)-ketamine." (PMID 40342162, 2025). "Current studies indicate that quercetin enhances the expression of BDNF in the prefrontal cortex and hippocampus of mice, improving anxiety, depression, and cognitive deficits induced by psychosocial stress." (PMID 40697653, 2025). "Background/Objectives: Brain-derived neurotrophic factor (BDNF) has been investigated as a potential mechanistic marker or therapeutic target to manage symptoms such as fatigue, pain, depression, and sleep disturbances." (PMID 40002745, 2025). "In patients with depression, BDNF levels are reduced, but suppressing NF-κB can restore BDNF expression, thereby alleviating depressive symptoms." (PMID 40358153, 2025). "For example, higher adiponectin levels are associated with a lower severity of depressive symptoms, whereas exercise-induced changes in BDNF and adiponectin correlate with treatment response in resistant forms of depression." (PMID 41516008, 2025). "At the current time, although the pathogenesis of depression is not fully understood, it has been suggested that signal pathways affected by BDNF and its receptors (TrkB and p75NTR) have a role in the pathogenesis of depression." (PMID 40005159, 2025). "We explored the possible mechanisms through which exercise/PA modulates BDNF expression and its subsequent effects on various symptoms, including fatigue, pain, depression, and sleep disturbances." (PMID 40002745, 2025). "In this review, reducing cortisol (or corticosterone) and increasing BDNF were identified as targets in probiotic therapy for anxiety and depression." (PMID 40342368, 2025). "Collectively, these findings implicate cytokine‐mediated dysregulation of MAPK/NF‐κB/BDNF networks in depression pathophysiology.." (PMID 41425661, 2025). "To further explore the reason for the anxiety- and depression-like behavior in the stressed mice, we measured the levels of BDNF in the mouse brains using IF." (PMID 40806449, 2025). "Eine 3‐jährige prospektive Studie zeigt, dass BDNF(„brain derived neurotrophic factor“)-mRNA und Plasmaspiegel bei Erstdiagnose einer Major-Depression bei Patienten, die später eine bipolare Störung entwickelten, verringert sind." (PMID 39709326, 2025). "Further research is needed to clarify when exercise-induced BDNF changes are most likely to result in symptom relief, particularly for fatigue, pain, and depression." (PMID 40002745, 2025). "Many previous reports have shown that the BDNF signaling cascade is closely involved in the pathophysiology of depression (Björkholm and Monteggia, 2016)." (PMID 40356991, 2025). "A recent experiment showed that forced treadmill exercise reduced symptoms of depression and enhanced cognitive function in rats that were intraperitoneally injected with LPS, through its influence on brain-derived BDNF expression levels in the hippocampus." (PMID 41157245, 2025). "Depression patients often have lower BDNF/CREB levels in the brain, and some antidepressants have been found to increase their activity." (PMID 40362260, 2025). "This review delves into preclinical findings from animal models of depression, examining the effects of chronic stress, genetic manipulations, and the tPA/BDNF pathway." (PMID 40725146, 2025). "For example, increased expression of plasminogen activator inhibitor-1 (PAI-1) prevents conversion of proBDNF to mature BDNF (mBDNF), leading to reduced hippocampal BDNF levels in depression models." (PMID 41340853, 2025).
depression (continued). "Chronic stress or early life stress significantly reduces BDNF levels in the hippocampus, leading to impaired synaptic plasticity and depression-like behavior 19,20." (PMID 40225589, 2025). "Analysis of transcriptomic data from depression-related mouse models in the GEO database enabled the identification of key genes, including Oprm1, BDNF, and Tph2, which exhibited marked expression differences between the NAC and PFC regions." (PMID 40656047, 2025). "In a mouse model of postpartum depression, ER2 expression in the prefrontal cortex influences the expression of brain-derived neurotrophic factor (BDNF) and depression-like behavior." (PMID 41155634, 2025). "In this study, we found that the levels of BDNF and Nr3c1 genes in the brain decreased following exposure to restraint stress and the onset of anxiety and depression symptoms." (PMID 40806449, 2025). "Clinical studies showed that BDNF serum concentrations are reduced during episodes of both mania and depression and increase after successful pharmacological treatment, including lithium treatment." (PMID 40283904, 2025). "Researchers measured serum BDNF (using ELISA), as well as depression, anxiety, and stress via the Depression Anxiety Stress Scale (DASS) and craving with the Desires for Drug Questionnaire (DDQ)." (PMID 40725591, 2025). "Mean differences in BDNF levels (ng/mL) by pain status and its characteristics in older adults with depression, stratified by sex (n = 293)." (PMID 40222813, 2025). "Reduced BDNF has also been described in adolescents with major depressive disorder and adverse metabolic profiles, emphasizing the relevance of psychiatric and metabolic comorbidities." (PMID 41614834, 2025). "Specifically, most studies reported increased methylation at BDNF, SLC6A4, and NR3C1, while FKBP5 typically showed decreased methylation associated with depression." (PMID 41179817, 2025). "In RCTs with baseline 25-hydroxyvitamin D [25(OH)D] < 30 ng/mL, vitamin D supplementation ≥ 2000 IU/daily or 50,000 IU/weekly for ≥12/8 weeks increased circulating BDNF by ≈ +7% and reduced Beck Depression Inventory II (BDI-II) scores by 1.7–7.6 points." (PMID 40871684, 2025). "BDNF, a key protein involved in depression, anxiety, and cardiovascular disorders, has been extensively studied." (PMID 40520201, 2025). "Biomarkers known to play a role in depression, such as BDNF, NGF, VEGF, IGF1, Ang, Nrg1, IL-6, and TNF-α, will be measured using advanced techniques like enzyme-linked immunosorbent assay (ELISA), Western blotting, and immunoprecipitation kits." (PMID 41149800, 2025). "Brain-derived neurotrophic factor (BDNF) has been found to be effective in enhancing the stress response triggered by Arg1 microglia in the hippocampus, thereby effectively alleviating depression." (PMID 40077572, 2025). "BDNF is a downstream factor regulated by CREB, and activation of the CREB/BDNF signaling pathway has been found to decrease hippocampal neuron damage in rats with depression." (PMID 40149758, 2025). "Running a half-marathon increased the levels of miR-1, miR-133a, and miR-206, and miR-133a and miR-206 are implicated in the exacerbation of cerebral ischemia/reperfusion injury and the pathogenesis of depression by targeting the BDNF pathway." (PMID 40563979, 2025). "At the same time, the role of the hippocampus in regulating depression-related signaling pathways has been widely studied, including signaling pathways controlled by upstream factors such as NF-κB and BDNF." (PMID 40006068, 2025). "In major depressive disorder and bipolar disorder, there is additional evidence supporting BDNF as a potential biomarker of treatment response." (PMID 41303216, 2025). "Not surprisingly, we observed that the biotin alone and MgB complex improved cognitive scores in a dose-dependent manner, consistent with the effects of BDNF on learning, memory, and depression." (PMID 39821844, 2025).
depression (continued). "In the LPS-induced depression model, the expression of Iba-1 in the hippocampus is increased, the levels of Tet1/2/3 and 5-hmC are down-regulated, and the expression of BDNF mRNA is reduced." (PMID 40881472, 2025). "This loss of acetylation is often accompanied by downregulation of BDNF expression, impaired synaptic plasticity, and diminished stress resilience, ultimately leading to depression-like behaviors such as social withdrawal and anhedonia." (PMID 40949123, 2025). "Further investigation of the PI3K/AKT pathway’s upstream (BDNF, TrkB) and downstream (CREB) depression-related proteins demonstrated that CUMS induction significantly reduced hippocampal levels of BDNF, TrkB, and p-CREB/CREB, as detected by WB." (PMID 41179813, 2025). "Though the effect was minimal, it would be consistent with a previous meta-analysis suggesting that responders to ketamine treatment for depression showed greater longitudinal increases in peripheral BDNF over time." (PMID 39613915, 2025). "Brain neurogenesis is involved in the occurrence of depression through brain-derived neurotrophic factor (BDNF), an important neurotransmitter regulator." (PMID 40607033, 2025). "Among men experiencing CP alongside depression, BDNF concentrations were also significantly diminished compared to those without pain, particularly in cases of severe or interfering pain." (PMID 40222813, 2025). "Previous research has indicated that thymol can mitigate depression-like symptoms and increase brain-derived neurotrophic factor (BDNF) levels in the hippocampus in an animal model of corticosterone-induced depression." (PMID 40283944, 2025). "Aerobic exercise, resistance training, and high-intensity interval exercise (HIIE) have been shown to increase serum and hippocampal BDNF levels, effectively reducing depression and cognitive decline." (PMID 40426650, 2025). "For example, the abnormal expression of genes such as brain-derived neurotrophic factor (BDNF) and serotonin transporter (SERT) has been closely linked to the pathogenesis of depression." (PMID 40656047, 2025). "Interestingly, a meta-analysis of DNA methylation in the BDNF and NR3C1 genes in the context of depression showed that BDNF hypermethylation may be associated with the risk of MDD in Asian populations, whereas NR3C1 hypermethylation was linked to depressive symptoms but not to MDD itself." (PMID 41303216, 2025). "In conclusion, research across multiple models—including animal studies, clinical investigations, cell line experiments, and primary cultures—consistently underscores the vital role of BDNF in cognitive regulation, depression, and hormone-mediated modulation." (PMID 39935532, 2025). "This hyperactivation promotes hippocampal atrophy and reduces brain-derived neurotrophic factor (BDNF) levels, both of which are closely associated with the pathogenesis of depression." (PMID 41029545, 2025). "Studies have shown the possible roles of BDNF, both at the gene and protein levels, in chronic condition-related symptom experiences such as fatigue, chronic pain, depression, sleep disturbance, and memory impairment." (PMID 40002745, 2025). "Regarding depression, the chronic treatment with antidepressants has been reported to increase BDNF expression in the rat HPC, while BDNF showed anti-depressant actions in learned helplessness-related paradigms, such as the forced swimming test." (PMID 40867109, 2025). "This scoping review assesses existing studies exploring the relationships between exercise/PA, symptoms, and BDNF levels, specifically focusing on fatigue, pain, depression, and sleep disturbances in adults." (PMID 40002745, 2025). "It is thought that miR-43b-5p and miR-470-5p contribute to depression pathogenesis via neuroinflammation induction and BDNF targeting." (PMID 41425661, 2025).